KRAS (KRas proto-oncogene, GTPase)
Diseases named in the same sentence as KRAS in open-access papers (continued):
Sharing a sentence is not in itself a finding about the gene and the disease.
tumor (continued). "In one patient, the primary tumor tissue was KRAS exon 2–4 wild type, similarly cfDNA analysis confirmed the KRAS wild type status at baseline before initiating of 1st line therapy." (PMID 28328955, 2017). "In our study, we observed that none of the two POLE‐positive tumors presented NRAS or BRAF mutations, but tumor T286 exhibited the p.Glu542Lys PIK3CA mutation and tumor T368 displayed the p.Lys117Asn KRAS mutation." (PMID 29072370, 2017). "Intriguingly, 63% of the genes activated in fibroblasts during microtumor growth with HCT116 KRAS-driven tumor cells were also activated when cultured with HT-29 BRAF-driven tumor cells." (PMID 29245949, 2017). "Injection of human mutant KRAS cells infected with the inducible FOSL1 shRNA into immunodeficient mice treated with doxycycline yielded tumours of significant smaller volume than control cells." (PMID 28220783, 2017). "In our previous studies, we observed that KRAS tumour propagating cells (TPCs) were present in both Sca1+ and Sca1- compartments, and a purely squamous model generated by bialleleic inactivation of Lkb1 and Pten (Lkb1/Pten) harboured Sca1+ and NGFR+ TPCs37." (PMID 28387316, 2017). "Across markets, 40%–46% of physicians ranked KRAS/RAS Mut mCRC/first-line as the “number 1” tumor type and treatment setting in which a bevacizumab biosimilar would have the greatest impact on patient outcomes among patients with solid tumors." (PMID 28134851, 2017). "Panitumumab was first approved in the European Union (EU) in December 2007 as monotherapy for the treatment of patients with mCRC and confirmed wild-type KRAS tumour status after failure of fluoropyrimidine-, oxaliplatin- or irinotecan-containing chemotherapy." (PMID 29183279, 2017). "Here, we found no significant connection between genetic background and sensitivity to SHR8443, which was evidenced by a mean IC50 value of 7.3 nM in KRAS/BRAF mutant tumor cells." (PMID 29296217, 2017). "Combination of cobimetinib and GDC-0994 resulted in a significant decrease of tumor growth in multiple KRAS mutant xenograft tumor models compared to single agent treatment arms." (PMID 28982154, 2017). "In conclusion, we demonstrated mutational heterogeneity in primary tumour tissue of patients with PDAC, and found circulating tumour derived DNA in 27% of patients based on detection of mutations in the KRAS gene." (PMID 29152076, 2017). "Oncogenic KRAS can have both stimulating and repressive effects on autophagy, and these differing effects are tumor cell-specific and context-dependent." (PMID 28316954, 2017). "Mutations in KRAS, the major PDA oncogene, were only detected in 10/34 (29%) blood samples, compared to 20/23 (87%) tumor tissue biopsies." (PMID 29137355, 2017). "The common phenotypic pathway which these drugs are predicted to perturb is cell growth/proliferation, which alongside cell migration was the most activated pathway represented in the KRAS-MT tumor signature." (PMID 27965461, 2017). "Several miRNAs, including miR-143, miR-145, let-7 and miR-18a∗, act as tumor suppressors and repress the expression of KRAS and vice-versa, KRAS regulates the expression of different oncogenic miRNAs, including miR-200c, miR-221/222, miR-210 and miR-181∗." (PMID 28714940, 2017). "Lastly, NOX2 expression was associated with the induction of oncogenic KRAS and RAF signalling, and upregulation of angiogenesis-related genes that contribute to tumour progression, metastasis, and reduced survival rate." (PMID 28894215, 2017). "The clinicopathologic variables compared with FBXW7 status included age, sex, race/ethnicity, site of the primary tumor, histologic grade, and KRAS, NRAS, BRAF, PIK3CA, and microsatellite instability status." (PMID 28424412, 2017).
tumor (continued). "In one particular case, we detected two different KRAS mutations, G13D and G12D, from the same patient: G13D from plasma sample by the UHS method and G12D from patient-matched tumor tissue by Sanger sequencing." (PMID 28459822, 2017). "In one CIMP-positive patient, a KRAS p.G12D mutation was detected in both the primary tumor and matched liver metastasis; in the patient with discordant CIMP status, the primary tumor carried KRAS p.Q61H." (PMID 28469732, 2017). "Further characterization of the mechanistic relationship between STK38L and KRAS will be critical to fully understand context-dependent tumor cell survival signaling networks in KRAS mutant PDACs." (PMID 29108249, 2017). "Both KRAS analyses in the tumor tissue of the patient reported here were performed in the same specialized and certified laboratory for molecular pathology." (PMID 28549417, 2017). "In KRAS mutated mice, GDC0941 efficiently blocked tumor growth with decreased cell proliferation after 14 days of treatment." (PMID 27845911, 2017). "The study results had shown that CRC patients with KRAS rs1137188 AA genotype were more likely to have higher portion of tumor size (≥ 5 cm)." (PMID 28328959, 2017). "In conclusion, the main finding of this study was that MALAT1 acts as a tumour promoter at least in part by binding miR-217 and sequestering the molecule in the nucleus, thereby promoting oncogenic KRAS expression in PDAC." (PMID 28701723, 2017). "In this manuscript, we used a unique model system to study lineage switching in KRAS-driven tumours in response to Lkb1 deletion." (PMID 28387316, 2017). "We confirmed that growing 3D tumour organoids derived from FlpO induced KRAS lesions in 100 nM 4-hydroxy tamoxifen was able to drive deletion of the Lkb1 allele, making this a tractable system in which to observe the early changes associated with Lkb1 loss." (PMID 28387316, 2017). "NGS-based profiling of the tumor genome identified a single nonsynonymous mutation among the many genes noted for recurrent mutations in CRC (e.g., KRAS, NRAS, BRAF, PIK3CA) and a striking focal amplification of the FGFR2 gene." (PMID 28835367, 2017). "Our data indicate that after Lkb1 is deleted in established KRAS ADCs, epigenetic reprogramming drives cells to take on squamous characteristics, ultimately resulting in full squamous transition of some tumours." (PMID 28387316, 2017). "Tumor cell content of pseudomyxoma peritonei FFPE samples estimated from HE stainings, and variant allele frequencies (VAF) of KRAS and GNAS from targeted sequencing." (PMID 28426742, 2017). "Our first set of experiments demonstrated that Lkb1 deletion in cells that had KRAS activation long before was sufficient to produce tumours with squamous characteristics." (PMID 28387316, 2017). "We observed that high levels of AURKA were a marker of poor prognosis in both tumour types, highlighting a clinical role for this kinase in KRAS-driven tumours." (PMID 28220783, 2017). "In the KRAS mutation analyses of the CTC and primary tumor specimens, we detected various types of codon 12 and 13 mutations." (PMID 28674438, 2017).
tumor (continued). "Many acquired gene amplifications were identified in the patient's tumor profile; several of these amplifications were present in the responding tumor (MLCL, CDK4, and KRAS) and are less likely to be associated with resistance." (PMID 28915719, 2017). "To date, the metabolic significance of PDHK4 in cancer development is still unclear but this study proposes a new role of PDHK4 in regulating mutant KRAS activation and tumour promotion." (PMID 28692044, 2017). "These links between ECT2 and RAS signalling make this an attractive and novel target worthy of further investigation for pro-senescence therapy of KRAS mutant tumours." (PMID 28806777, 2017). "There are possible biological and technical explanations for the 42% discordant KRAS mutations in the CTC and the primary tumor in this study." (PMID 28674438, 2017). "Collectively these data demonstrate that KRAS mutant tumor lines respond similarly to MEK or ERK inhibition and that pathway reactivation would be expected to limit the activity of single agent approaches." (PMID 28982154, 2017). "Indeed with a stated conversion factor of 44 million KRAS-mutant cells for every mutant KRAS template/ml, the estimated MT-KRAS tumor burden ranged from 0.13 grams to 21 grams, with 7/9 patients with circulating MT-KRAS having <5 grams of tumor harboring a KRAS mutation." (PMID 28981524, 2017). "Together, these results suggest a PDH-independent role of PDHK4 in maintaining cell growth in mutant KRAS tumours." (PMID 28692044, 2017). "In this sample, the region of the genome containing KRAS had two copies, with a tumour cell content of 95%, which would lead to an expected VAF of around 50%." (PMID 28315634, 2017). "Since KRAS and BRAF mutations are mutually exclusive, BRAF testing is performed only in KRAS WT tumours." (PMID 29137623, 2017). "All three tumour samples were measured KRAS wild type through our mobile-phone-based targeted sequencing, also confirmed by both regular microscopy-based sequencing analysis and diagnostic PCR analysis." (PMID 28094784, 2017). "Mechanistically, MYC binding is enriched at neuroendocrine genes in mouse tumor cells and loss of MYC reduces ductal-neuroendocrine lineage heterogeneity, while deregulated MYC expression in KRAS mutant mice increases this phenotype." (PMID 29170413, 2017). "Two, representing CIMP-H and CIMP-L tumours, were associated with BRAF and KRAS mutations, respectively." (PMID 28351398, 2017). "Here, we show for the first time, that PDHK4 down-regulation significantly inhibits the growth of KRAS mutant tumours, which is uncoupled from PDH regulation." (PMID 28692044, 2017). "To characterize the chromatin landscapes of KRAS/Lkb1 tumours, we performed chromatin immunoprecipitation (ChIP) on microdissected tumours confirmed to be either ADC or SCC by histology and qPCR." (PMID 28387316, 2017). "In this pre-clinical study, vitamin E was able to interact with oncogenic KRAS; thus, it has been proposed as an anti-tumor agent." (PMID 28282928, 2017). "There is growing evidence that KRAS-induced carcinogenesis is promoted by cellular stress like chronic inflammation, which plays a crucial role in tumour initiation and progression." (PMID 27941872, 2017). "PCR-based methods such as bead-based digital PCR in emulsions (BEAMing) and droplet-based digital PCR have been used to detect highly recurrent tumor-specific mutations in well-known driver genes such as APC, BRAF, KRAS and EGFR in plasma samples." (PMID 29156805, 2017).
tumor (continued). "The selected models harbored molecular alterations commonly described in the matched tumor types, such as loss of PTEN expression present in around 30% in patients with TNBC and LADC or KRAS mutation described in around one third of LADC and LGSOC." (PMID 29156674, 2017). "CBP501 provides a novel approach to target KRas signaling in cancer in addition to the known anti-cancer action which is the augmentation of cytotoxicity of platinum agents to tumor cells." (PMID 29088764, 2017). "Selection within the KRAS eight-gene cross-tumours signature of the candidate gene FOSL1 for follow-up studies relied on the incorporation of patient outcome information." (PMID 28220783, 2017). "IDF-11774 also inhibited the tumor growth of NCI-H1975 cells bearing an EGFR T790M mutation and wild-type KRAS." (PMID 28569777, 2017). "We analyzed the presence of mutations in exons 18 to 22 of EGFR and of exon 2 of KRAS in tumors, where the mutation of the KRAS gene was detected both in LLC cell culture and in the tumor implants extracted from the mice." (PMID 29285236, 2017). "We conclude that mutant KRAS not only protects tumor cells against CD95L-induced apoptosis, but also against CD95L-induced senescence." (PMID 28300842, 2017). "Gain-of-function missense mutations in KRAS and BRAF genes are mutually exclusive CRC drivers and have similar but subtly different roles during initiation and tumor development." (PMID 29167573, 2017). "From the 22 samples analysed, five KRAS (codon 12 and 13), two BRAF(V600E) and 2 PIK3CA mutants were identified, including one tumour with a BRAF and PIK3CA mutation." (PMID 28931905, 2017). "Since KRAS mutations are mutually exclusive with other dominant oncogenic drivers in LAC, we reasoned that the cross-tumours eight-gene signature would be exclusive of the KRAS phenotype." (PMID 28220783, 2017). "Although KRAS mutants are more prevalent among CMS3 tumours, they are present in every molecular subtype." (PMID 28956850, 2017). "Single CTCs recovered from 11 (18%) patients from whom primary tumor samples were available were evaluated to determine the KRAS genotype; primary tumor samples were also sequenced in these cases." (PMID 28468669, 2017). "Because of the clinical significance of the KRAS gene, KRAS wild type status in the primary tumor is a prerequisite for treatment modality of patients with mCRC with targeted therapy apart from the best supportive care alone." (PMID 28903450, 2017). "Protein expression of myc-PDHK4 was also confirmed by western blot analysis of xenograft extracts 22 days post-implant and pull-down assays also showed an increase in KRAS activity in the PDHK4 stable xenograft compared to the control tumours." (PMID 28692044, 2017). "Patients with resected CRC had DNA extracted from eight defined tumour areas which were analysed for two genetic mutations (BRAF and KRAS) and one epigenetic trait (CpG island methylator phenotype/CIMP)." (PMID 28097409, 2017). "This pathology-defined prognosis is also dependent on both tumor stage and the status of genetic mutations in the EGFR, KRAS, ALK, RET, and BRAF genes." (PMID 29137260, 2017). "This tumor was also investigated for KRAS, NRAS, BRAF, and PIK3CA mutations, and a mutation in KRAS exon 4 was found, namely the c.351A>C, p.Lys117Asn." (PMID 29072370, 2017). "Among mCRC patients, in multivariate analysis, age at diagnosis (<75 years; p < 0.0001), site of primary tumor (left colon; p = 0.006) and geographical area of primary treatment (p = 0.01) were factors related to KRAS molecular testing." (PMID 29137623, 2017). "The fact that vitamins, like vitamin E and vitamin C, enable the inhibition of mutant KRAS-driven pathways via MAPK or PIK3/AKT offers new treatment strategies for this kind of tumor for which few therapies are available." (PMID 28282928, 2017). "When extended to a larger panel of cell lines we observed enhanced sensitivity to PDHK4 depletion in KRAS mutant versus wild-type tumour cells." (PMID 28692044, 2017).
tumor (continued). "Using these module definitions, we then calculated mean module activities for the control and tumor-derived KRAS G12D cells." (PMID 28152508, 2017). "In tumor samples from patients with mCRC biomarkers of MAPK activation strongly correlated with markers of PI3K/AKT activity, both in KRAS wild type and KRAS-mutated tumors." (PMID 28507280, 2017). "Previous data have suggested that the status of these genes is highly concordant between the primary tumour and metastases, with concordance rates of 92% for KRAS and 97% for BRAF." (PMID 29029407, 2017). "All two CTOS lines which exhibited tumor regression were KRAS-wildtype, meanwhile all KRAS-mutant CTOS lines grew more than the initial size: were resistant to cetuximab according to the clinical evaluation criteria, although the sensitivity was quite diverse." (PMID 28301591, 2017). "Constitutive activation of KRAS results in sustained and unregulated proliferation, evasion of apoptosis, re-modelling of the micro-tumor environment, increased cell migration and metastatic spread." (PMID 27845911, 2017). "From the three studies, 138 patients with KRAS mutant NSCLC and 371 with KRAS wild-type tumor were included in the meta-analysis of HRs and 95% CIs for OS." (PMID 28525386, 2017). "Of the POLE‐mutated CRCs, one tumor was microsatellite‐stable and the other had low microsatellite instability, whereas KRAS and PIK3CA mutations were found in one tumor each." (PMID 29072370, 2017). "Advanced stage, larger tumor size, mucinous component, and wild‐type KRAS were significantly more frequent in the validation cohort." (PMID 28544821, 2017). "KRAS mutation, Fong CRS > 2, and poor preoperative chemotherapy response were chosen as criteria for a tumor biology score (TBS) staging system." (PMID 29108374, 2017). "Treatment of mice expressing oncogenic KRAS with neutralizing antibody for IL-13 reduces tumor formation." (PMID 29156578, 2017). "Overall in Rounds 1 and 2 of the physician survey, 298 (99.0%) of 301 physicians responded correctly that panitumumab should be administered only to patients with confirmed KRAS wild-type tumours." (PMID 29183279, 2017). "Of these, four KRAS mutations, two NRAS mutations, two histone H3 mutations, and one ALK mutation were predicted to encode epitopes in at least one tumor." (PMID 28854978, 2017). "In this regard, our strategy using experimental systems that represented initial stages of KRAS-induced cell transformation and tumour progression yielded genes with a role in advanced disease such as FOSL1." (PMID 28220783, 2017). "Another mechanism associated to vitamin C is the disruption of the Warburg effect in tumor cells with the KRAS mutant genotype through downregulation of key metabolic checkpoints." (PMID 28282928, 2017). "Collectively, these findings suggest that PDHK4 is necessary for tumour growth in mutant KRAS cells, which appears to be uncoupled from the action of PDHK4 on the PDC complex." (PMID 28692044, 2017). "NKX2.1 functions as a tumor suppressor in KRAS-driven mucinous adenocarcinomas, but has an oncogenic role in EGFR mutated lung tumors." (PMID 29267283, 2017). "In genetic polymorphisms analysis, the association between KRAS and VEGF 3’-UTR SNPs and CRC risk was further analyzed by tumor site, tumor size, differentiation degree, invasive depth and TNM staging." (PMID 28328959, 2017). "Specifically, there are significant differences among the subtypes in tumor location (P<0.001), proportion of microsatellite instability (MSI) (P<0.001), presence of mucin (P<0.001), and incidence of KRAS mutation (P=0.01)." (PMID 28455965, 2017). "Primarily, it should be clarified how representative KRAS genotyping in cfDNA is in comparison to tumor tissue assessment, which is the gold standard in deciding regarding anti-EGFR treatment." (PMID 28328955, 2017). "Using targeted resequencing with a custom 900 cancer gene panel, eight somatic mutations among them KRAS and NF1, were identified in the primary tumour." (PMID 28061772, 2017).